UBA1 (ubiquitin like modifier activating enzyme 1)
Diseases named in the same sentence as UBA1 in open-access papers (continued):
Sharing a sentence is not in itself a finding about the gene and the disease.
infection (7 papers, 2011 to 2025). The state of being infected such as from the introduction of a foreign agent such as serum, vaccine, antigenic substance or organism. "Depletion of UBA1 during infection caused significant decreases in ZIKV and USUV titres with respect to controls." (PMID 39773572, 2025). "We also found increased viral protein levels (NS5) in cells overexpressing UBA1 by WB at 36 h post-infection." (PMID 39773572, 2025). "We observed a significant increase in ZIKV yields at 48 h post-infection in both cells overexpressing UBA1 (either native or FLAG-tagged), with respect to mock-transfected cells." (PMID 39773572, 2025). "Larger amounts of UBA1 levels detected at 24 and 48 h post-infection correlate with elevated virus titres in the cellular supernatants." (PMID 39773572, 2025). "We found >10- and 100-fold decreases in ZIKV titres at 48 and 72 h post-infection, respectively, in cells transfected with 3 pmol of UBA1-specific DsiRNA." (PMID 39773572, 2025). "Despite exploiting the UPS pathway is a common strategy shared by many viruses to complete their life cycles, and UBA1 playing a critical role in such pathway, there is limited information on the role of UBA1 during infection by different viruses." (PMID 39773572, 2025). "At 36 h post-infection, UBA1 and NS5 colocalization could be detected in the nuclei of infected cells." (PMID 39773572, 2025). "To assess this possibility, we quantified UBA1 protein levels in ZIKV- and USUV-infected cells by WB at different times post-infection." (PMID 39773572, 2025). "Recent studies have established a possible connection between infections by severe acute respiratory syndrome coronavirus 2 (SARS-CoV-2) and Epstein–Barr virus (EBV) with UBA1." (PMID 39773572, 2025). "We confirmed that UBA1 protein expression levels were significantly larger at 24 h post-infection (>2-fold), both in cells infected with ZIKV or USUV, and at 48 h post-infection in ZIKV-infected cells." (PMID 39773572, 2025). "Representative genes belonging to groups A (SKL2, ECR1), B (UBA1, GLO1 and RPA32) and C (HSC70, ASK2, and deltaCOP) were chosen to evaluate the impact of their silencing on TYLCSV infection, measured as viral DNA accumulation." (PMID 21818318, 2011). "While our data suggest that UBA1 is critical to the virus life cycle, further examination will be required to fully understand how its interaction with NS5 affects the host cell during infection." (PMID 39773572, 2025).
blood cancer (2 papers, 2022 to 2024). "UBA1 loss-of-function mutations in VEXAS result in distinct phenotypes not observed in model organisms, including inflammation, cytopenias, thrombotic tendencies, clonality, and blood cancer associations." (PMID 39347709, 2024).
cardiovascular disorder (1 paper, 2020). A disease involving the cardiovascular system. "Defects in the expression or activity of UBA1 correlate with several neurodegenerative and cardiovascular disorders." (PMID 32258175, 2020).
hematological cancers (1 paper, 2022). "Schimmer and colleagues demonstrated that UBA1 was a bona fide drug target in several hematological cancers several years ago." (PMID 36712364, 2022). "This hypothesis became testable in hematological cancers with the recent discovery and characterization of TAK-243, a specific and potent UBA1 inhibitor." (PMID 36712364, 2022). "Of note, a diagnostic c-MYC immunohistochemical staining has been developed for hematological cancers, and this could potentially support the use of c-MYC in future clinical studies of TAK-243 or newer UBA1 inhibitors in TNBC." (PMID 36712364, 2022).
neuromuscular disease (1 paper, 2024). "UBA1 pathogenic mutations show a clear sex bias in VEXAS and X-linked spinal muscular atrophy (XL-SMA), a congenital neuromuscular disease caused by germline UBA1 mutations." (PMID 39347709, 2024).
UBA1 also shares sentences with these, for which no sentence is quoted: ovarian carcinoma (3 papers); vasculitis (3); Arthritis (2); colorectal cancer (2); cutaneous squamous cell carcinoma (2); cutaneous vasculitis (2); gastric cancer (2); giant cell arteritis (2); immune deficiency (2); immune disorders (2); Parkinson disease (2); squamous cell carcinoma (2); thymoma (2); triple-negative breast carcinoma (2); AA amyloidosis (1); adenocarcinoma (1); amyotrophic lateral sclerosis (1); Angelman syndrome (1); Aortic dissection (1); atopic dermatitis (1); Behçet’s disease (1); bone marrow failure (1); cardiac hypertrophy (1); cardiomyopathy (1); cerebellar ataxia (1); Charcot-Marie-Tooth disease (1); Chediak-Higashi syndrome (1); cholangiocarcinoma (1); chronic hepatitis B (1); cognitive decline (1).
A further 61 diseases each share a sentence with UBA1 in 1 paper.